NR3C1 (nuclear receptor subfamily 3 group C member 1)
Diseases named in the same sentence as NR3C1 in open-access papers (continued):
Sharing a sentence is not in itself a finding about the gene and the disease.
Anxiety (continued). "One well-known human example involves the NR3C1 gene, which encodes the glucocorticoid receptor; in a study of mothers with mood disorders, higher third-trimester maternal depression/anxiety was associated with increased DNA methylation of the NR3C1 promoter in their new-borns’ cord blood." (PMID 40649875, 2025). "Similarly, in a cohort of 83 pregnant women, prenatal maternal anxiety was found to be significantly linked with infant NR3C1 methylation in specific CpG sites located into exon 1F." (PMID 36114180, 2022). "Furthermore, only boys showed differential methylation of the FKBP5 gene in response to prenatal pregnancy-related anxiety; also, methylation of NR3C1 and HSD11B2 genes was associated with the risk of emotional symptoms and hyperactivity only in boys." (PMID 34715840, 2021). "These combined results strengthen the hypothesis that polymorphisms within the NR3C1 gene can serve as genetic risk-factors for anxiety, at least state anxiety." (PMID 32957930, 2020). "In addition, we evaluated the expression of stress-related genes: glucocorticoid and mineralocorticoid receptors (Nr3c1 and Nr3c2) and Nr1d1, which encodes a transcription factor (also known as REVERBα) modulating sociability and anxiety-related behavior." (PMID 32190129, 2020). "Previously, we have shown that pregnancy anxiety is linked to fetal DNA methylation in the glucocorticoid receptor gene (NR3C1), which is a key player in the hypothalamic-pituitary-adrenal axis, and to DNA methylation of imprinted genes IGF2 and GNASXL important in fetal growth and development." (PMID 29026448, 2017). "Finally, we assessed the moderating influence of candidate genes whose level of methylation is associated with the Nr3c1 genotype on anxiety-like behavior: Ank3, Avp, Avpr1a, Avpr1b, Bdnf, Cacna1c, Cyp11b1, Cyp11b2, Fkbp5, Hsd11b1, Igf2, Morc1, Nr3c1, Oxt, Oxtr, Pclo, Slc6a4." (PMID 30655507, 2019). "While fewer studies focus specifically on GAD, findings suggest associations between NR3C1 and FKBP5 methylation and anxiety symptomatology." (PMID 38792892, 2024). "NR3C1 expression levels are altered in anxiety and mood disorders and alterations have been already implicated in the DD phenotype in humans." (PMID 38391714, 2024). "Studies have confirmed that maternal distress and anxiety lead to slight increases in methylation at specific CpG sites of NR3C1 in newborns." (PMID 38249586, 2023). "Therefore, our finding suggests that academic pressure may have lasting effects on the methylation of NR3C1 and the susceptibility to anxiety symptoms, highlighting the importance of addressing academic pressure as a potential source of psychological stress in adolescents." (PMID 37254074, 2023). "Therefore, we hypothesize that after controlling for confounders, heavy academic pressure may be associated with NR3C1 methylation and anxiety symptoms, and the NR3C1 methylation may play a mediating role in the link between academic pressure and anxiety symptoms." (PMID 37254074, 2023). "Previous studies have indicated that the DNA methylation status of the NR3C1 gene is related to internalizing mental health problems, including anxiety symptoms." (PMID 37254074, 2023). "Consequently, it is speculated that DNA methylation of the NR3C1 gene might also be altered by academic pressure, a common life stress among adolescents, and may play a vital role in the association between academic pressure and persistent anxiety symptoms." (PMID 37254074, 2023). "The positive association between maternal anxiety and methylation of CpGs from N3RC1 corroborates the findings of studies that reported increased methylation of NR3C1 in offspring prenatally exposed to maternal distress." (PMID 34572069, 2021). "From the mediation model, we observed that the methylation level of NR3C1-CpG10 negatively mediated the effects of maternal anxiety during the third trimester on children’s anxiety (a × b = −0.0462)." (PMID 34572069, 2021).
Anxiety (continued). "In the current study, effects of maternal anxiety on DNA methylation level of NR3C1 were only observed in the third trimester." (PMID 34572069, 2021). "Higher maternal anxiety predicted higher NR3C1 methylation level, explaining 6.7% of the variance of methylation level for NR3C1-CpG3, 10.3% for NR3C1-CpG5, 6.6% for NR3C1-CpG6, and 10.7% for NR3C1-CpG10." (PMID 34572069, 2021). "We observed that children exposed to higher maternal anxiety during the third trimester had higher methylation levels of four CpGs from NR3C1 (i.e., CpG3, CpG5, CpG6, CpG10)." (PMID 34572069, 2021). "This study shows that SNP rs41423247 in the NR3C1 gene and SNP rs53576 in the OXTR gene are associated with self-assessed anxiety in healthy individuals in a gender-specific manner." (PMID 32957930, 2020). "Pearson’s correlation index between anxiety-like behavior z-score, Nr3c1, Crh, Crhr1, and Corticosterone." (PMID 33304248, 2020). "Maternal anxiety during the first two trimesters also affects the methylation status of NR3C1, thus diminishing NR3C1 gene expression." (PMID 31057437, 2019). "Nr3c1+/− animals of both sexes showed a significant increase exclusively in anxiety-like behavior which is consistent with data derived from several different transgenic mouse models." (PMID 30655507, 2019). "The results demonstrated that the haplotypic variations in the regulatory regions of the NR3C1 gene significantly correlated with trait-anxiety." (PMID 25009637, 2014). "The present study characterizes and precisely describes the haplotypes of the NR3C1 gene, while identifying the haplotype responsible for the changes occurring in trait-anxiety in asthma sufferers." (PMID 25009637, 2014). "Only one of the NR3C1 haplotypes exhibited a correlation with state-anxiety (P=0.026), which was AA ER22/23EK (rare), AA N363S (common) and CC BclI (rare)." (PMID 25009637, 2014). "This is consistent with the results of previous studies, which suggest that increased expression of nr3c1 may lead to a better response to stress and reduced anxiety symptoms." (PMID 40243462, 2025). "For example, the Slc6a4 knockout rat exhibits anxiety and depression-like behaviors alongside altered DNA methylation in the urocortin promoter, while the Nr3c1 knockout mutant reveals sex-specific deficits in fear memory acquisition and extinction, paralleling coping behaviors during stress." (PMID 39728686, 2024). "A prospective study also found that methylation in one region of the NR3C1 promoter may predict the development of internalizing problems, including anxiety symptoms." (PMID 37254074, 2023). "In conclusion, this study indicates that elevated academic pressure and the consequent alterations in NR3C1 methylation may serve as potential markers for identifying students with persistent anxiety symptoms." (PMID 37254074, 2023). "But the dysfunction of NR3C1 induces anxiety and PTSD when patients are exposed to extreme events or chronic stress. kappa-opioid receptors (KORs) are a subtype of the opioid receptor family, and accumulating evidence indicates that KORs are involved in transducing the effects of stress." (PMID 37986356, 2023). "The present study suggests that NR3C1-16 CpG 10 DNA methylation might be a potential mechanism that partially explains the lasting effects of academic pressure on subsequent anxiety symptoms among adolescents." (PMID 37254074, 2023). "In other words, although the direct effect (c’) of maternal anxiety on the children’s anxiety symptoms was positive (higher maternal anxiety, higher children’s anxiety), the mediation via DNA methylation of NR3C1-CpG10 seems to buffer the effect of maternal anxiety." (PMID 34572069, 2021). "Similarly, the methylation level of NR3C1-CpG3 negatively mediated the effects of maternal anxiety during the third trimester on children’s ADHD (a × b = −0.0360)." (PMID 34572069, 2021).
Anxiety (continued). "Based on these results, we suggest that the effect of maternal anxiety (third trimester) on children’s anxiety could be buffered by DNA methylation of the two NR3C1 regions." (PMID 34572069, 2021). "Furthermore, the methylation level of NR3C1-CpG10 and -CpG3 negatively mediated the effects of maternal anxiety during the third trimester on children’s behavioral problems." (PMID 34572069, 2021). "Decreased levels of H3K9ac have also been found at the glucocorticoid receptor gene (Nr3c1) in rats that show increased stress reactivity and anxiety-related behavior in adulthood as a result of receiving low levels of maternal care over their first week of life." (PMID 33668469, 2021). "However, when controlling for the covariates gestational age at birth and maternal anxiety when the child was four years of age, the mediation effect of DNA methylation of NR3C1-CpG10 disappeared (p = 0.1796)." (PMID 34572069, 2021). "Our data supports the hypothesis that Nr3c1 influences DNA methylation at birth and that DNA methylation in placenta correlates with adult frontal cortex DNA methylation and anxiety-like phenotypes." (PMID 30655507, 2019). "Phenotypically, Nr3c1 heterozygotes show significantly more anxiety-like behavior than wildtype." (PMID 30655507, 2019). "As second trimester anxiety was associated with female birth weight, we next examined the relationship between second trimester STAI scores and three key genes involved in glucocorticoid signalling in the placenta, HSD11B2, NR3C1 and FKBP51." (PMID 30310158, 2018). "Maternal anxiety had no impact on NR3C1 CpG2 methylation state, yet was associated with increased methylation of the placental HSD11B2 gene." (PMID 27918480, 2016). "Therefore, haplotype analysis revealed a correlation between polymorphic forms of NR3C1 and the level of trait-anxiety." (PMID 25009637, 2014). "Previous studies have shown that increased methylation at specific sites of the NR3C1 gene may contribute to vulnerability to anxiety and other psychopathologies and may moderate the effects of interventions on alcohol abuse development among African American adolescents compared with Europeans." (PMID 40045917, 2025). "These protocols generally reported consistent increases in anxiety-like behaviors (e.g., reduced exploration, increased bottom-dwelling in novel tank tests), cortisol elevations, altered gene and protein expression patterns (e.g., crh, nr3c1), and changes in social interaction metrics." (PMID 40427646, 2025). "Indeed, the relative gene expression of Crf in the PVN and Nr3c1 in the HIPP was evaluated to detect changes that may help to elucidate, at least in part, the anxiety and depressive-like behavior caused by PAE." (PMID 41008546, 2025). "The expression of nr3c1 in response to stress suggests the potential of this plant extract to stabilize the body’s response to stress, which may be promising in the treatment of disorders related to chronic stress and anxiety." (PMID 40243462, 2025). "The mediation models further presented that without adjusting for other variables only NR3C1-16 CpG10 DNA methylation mediated the associations between academic pressure and anxiety symptoms (β estimate = 0.17, 95% CI = 0.04 ~ 0.40; indirect/total effect = 12.8%)." (PMID 37254074, 2023). "Additionally, further mediation analysis shows that academic pressure’s lasting impact on anxiety symptoms may occur through altering the DNA methylation status of the NR3C1-16 CpG10 site." (PMID 37254074, 2023). "Therefore, we predicted that, compared to control offspring, the offspring of stressed dams who were fed a SCD would have lower Nr3c1 expression in the hippocampus, resulting in more anxiety-like behavior due to less efficient negative regulation of the stress response." (PMID 36012509, 2022).
Anxiety (continued). "We hypothesised that patient's self‐reported pain levels during fixed orthodontic treatment are influenced by clinical factors, psychological factors, such as anxiety and pain catastrophising, as well as certain single nucleotide polymorphisms (SNP) of the COMT, HTR2A and NR3C1 genes." (PMID 34273191, 2021). "We hypothesized that ELS would disrupt normative development in both generations, manifesting as altered methylation and expression of genes associated with stress signaling pathways (Nr3c1, Nr3c2, and Bdnf), blunted corticosterone (CORT), and anxiety-like behaviors." (PMID 31143105, 2019). "This study aimed to investigate the effects of LB and MS models combined on classical anxiety-like behavior tasks and hypothalamic gene expression of targets related to HPA axis functioning (Crh, Crhr1, and Nr3c1)." (PMID 33304248, 2020). "In rats, the consequences of maternal neglect in the early life environment on NR3C1 methylation, HPA reactivity and anxiety behaviors can be reversed by increased tactile stimulation in the postnatal environment." (PMID 27918480, 2016). "In this study, we estimated the NR3C1 DNA methylation level between groups of students with persistent anxiety symptoms (cases) and controls without anxiety symptoms." (PMID 37254074, 2023). "Nr3c1ki/ki did not behave differently from Nr3c1+/+ mice in terms of locomotion, anxiety, working memory, social and non-social memory." (PMID 35733193, 2022). "We hypothesized that exposure to maternal pregnancy-related anxiety in utero may program child gender-specific neurobehavior via gender-specific DNA methylation of HSD11B2, NR3C1 and FKBP5 genes in placenta." (PMID 34715840, 2021). "The negative correlation found between NR3C1 methylation and anxiety did not survive correction for multiple comparisons." (PMID 33705478, 2021). "Self‐reported pain during fixed orthodontic treatment was not influenced by sex, age, time into treatment, anxiety, nor by polymorphisms of COMT, HTR2A or NR3C1 genes." (PMID 34273191, 2021). "To do this, we sought to investigate: (i) the effects of MS and LB combined on maternal behavior; (ii) anxiety-like behavior during young adulthood in three tasks (OF, EPM and LD); and (iii) Crh, Crhr1, and Nr3c1 mRNA expression in the hypothalamus, as well as peripheral corticosterone levels." (PMID 33304248, 2020). "We believe this is the first study to examine NR3C1 methylation in adults with and without a history of childhood adversity and with and without depressive, anxiety or substance-use disorders." (PMID 27378548, 2016). "Finally, while no significant changes in anxiety-like behaviours were observed in this study, several genes associated with anxiety, such as CRHR1, NR3C1, NR3C2, were altered in a region and time dependent manner injured mice." (PMID 40375338, 2025). "In concordance with the hypomethylation hypothesis, however, N3RC1 heterozygote mice (NR3C1+/−) with depleted levels of GRs showed a significant increase in anxiety-like behaviors, but not depressive-like behaviors." (PMID 35998298, 2023). "Mediation analysis showed that methylation of NR3C1 could buffer the effects of maternal anxiety on children’s behavioral measures, but this effect did not remain significant after controlling for covariates." (PMID 34572069, 2021). "In order to examine these issues, the present study investigated methylation of the NR3C1 1F promoter region in adults with and without a history of childhood adversity, and with and without a lifetime psychiatric diagnosis of depressive, anxiety or substance-use disorder." (PMID 27378548, 2016). "For example, mothers diagnosed with an anxiety disorder whodid not receive medication for anxiety have demonstrated altered DNA methylationof the glucocorticoid receptor gene (NR3C1) promoter region in cord blood andthe genome and may increase risk of their child developing an anxietydisorder." (PMID 29503978, 2017).
Anxiety (continued). "However, the scores of the factor characterized by FKBP5, NR3C1 and HSD11B2 did not mediate the relationship between maternal pregnancy-related anxiety and preschoolers’ emotional symptoms and hyperactivity." (PMID 34715840, 2021).
breast carcinoma (86 papers, 2006 to 2026). "Like 5-HTT, it is suggested that low expression of NR3C1 is also associated with poor pathological outcomes in breast cancer." (PMID 36430579, 2022). "Breast cancer cell migration and proliferation were linked to up-regulation of NR3C1." (PMID 40406148, 2025). "However, D5S207, a highly polymorphic dinucleotide repeat located near the NR3C1 locus, was associated with sporadic breast-cancer development in a Caucasian population." (PMID 35761157, 2022). "A retrospective meta-analysis in primary breast tumors showed that high gene expression of GR (NR3C1) in the bulk tumor was associated with significantly worse relapse-free survival (RFS) among ER-negative early stage breast cancer, but better survival in ER-positive breast cancer." (PMID 32629782, 2020). "To assess the clinical relevance of GR expression in ER+ breast cancer, we stratified ER+ patients according to NR3C1 mRNA level (high or low) in the METABRIC dataset." (PMID 41261233, 2026). "NR3C1 expression was viewed to be overexpressed in breast cancer, and the repression of NR3C1 blocked breast cancer cell migration and invasion." (PMID 36797317, 2023). "The lower expression of NR3C1 in male breast cancer seems to be in line with the finding that breast cancer in males is mostly oestrogen-positive, and it has a good prognosis." (PMID 36899920, 2023). "We also observed that NR3C1 gene expression was increased in ER− breast cancer cell lines compared to ER+ ones." (PMID 36899920, 2023). "Increasing studies confirm that NR3C1 as an oncogenic factor has been widely testified in various cancers, such as breast cancer, colorectal cancer, acute myeloid leukemia." (PMID 36797317, 2023). "Regarding breast cancer, NR3C1 expression was found around the average level compared to different tumour types at the RNA level." (PMID 36899920, 2023). "Zbtb16 expression is activated by the glucocorticoid receptor (NR3C1) in many cell types, including hepatocytes, breast cancer cell line, endometrial stromal cells, and myometrial smooth muscle cells." (PMID 36768453, 2023). "In contrast to normal tissue, in breast cancer, NR3C1 showed the opposite—its expression was decreased in male compared to female patients." (PMID 36899920, 2023). "In contrast to normal breast tissue, NR3C1 expression was decreased in male breast cancer tissue compared to females, reaching the level of significance (p = 0.055); however, it did not depend on age in either group." (PMID 36899920, 2023). "Lower expression levels of five hub gens, including IGF1, LEP, ADIPOQ, NR3C1, and PPARG, were determined and were remarkably associated with poorer OS and BCSS among breast cancer patients." (PMID 35317079, 2022). "We profiled the expression of selected stress-associated genes (5-HTT, NR3C1, OXTR, and FKBP5) in breast cancer including the stress evaluation of all participants using the Questionnaire on Distress in Cancer Patients–short form (QSC-R10)." (PMID 36430579, 2022). "In this study, we firstly identified that FKBP4/NR3C1 axis was a novel negative regulator of NRF2 in human breast cancer (BC) cells." (PMID 35087512, 2021). "We have previously identified that methylation of the GR gene (NR3C1) promoter is a common event that contributes to the downregulation of GR in breast cancer." (PMID 31675993, 2019). "Regarding breast cancer, the mRNA of the GR gene (NR3C1) is abundantly present in patient tumor biopsies of all intrinsic subtypes." (PMID 30987626, 2019). "The nuclear factor-κB (NF-κB) signaling pathway controled NR3C1 in breast cancer cells." (PMID 40406148, 2025). "As a further step, we also analyzed NR3C1 expression in 86 different breast cancer cell lines." (PMID 36899920, 2023). "In the context of breast cancer, NR3C1 promotor methylation has been suggested to play a role in its transcriptional silencing; however, other possible mechanisms of inactivation may also exist and should be dissected in further studies." (PMID 37902007, 2023).